AAAS (aladin WD repeat nucleoporin)
Description:
Plays a role in the normal development of the peripheral and central nervous system. Required for the correct localization of aurora kinase AURKA and the microtubule minus end-binding protein NUMA1 as well as a subset of AURKA targets which ensures proper spindle formation and timely chromosome alignment.
Synonyms: ADRACALA; GL003; AAA; AAASb; ADRACALIN; ALADIN
Tractability: PROTAC: ubiquitination databases record sites on it; its protein half-life has been measured.
Gene: Protein-coding gene on chromosome 12 (53,307,456 to 53,324,864, reverse strand). Ensembl gene ENSG00000094914.
Subcellular location: Nucleus, nuclear pore complex; Cytoplasm, cytoskeleton, spindle pole; Nucleus envelope
Subcellular location (Human Protein Atlas): Nuclear membrane; Centrosome; Cytosol; End piece; Nucleoplasm
Pathways (Reactome):
Disease: Defective TPR may confer susceptibility towards thyroid papillary carcinoma (TPC); HCMV Early Events; HCMV Late Events; NEP/NS2 Interacts with the Cellular Export Machinery; NS1 Mediated Effects on Host Pathways; Nuclear import of Rev protein; Rev-mediated nuclear export of HIV RNA; SARS-CoV-2 activates/modulates innate and adaptive immune responses; Transport of Ribonucleoproteins into the Host Nucleus; Viral Messenger RNA Synthesis; Vpr-mediated nuclear import of PICs
Metabolism of RNA: Transport of Mature mRNA Derived from an Intronless Transcript; Transport of Mature mRNA derived from an Intron-Containing Transcript; Transport of the SLBP Dependant Mature mRNA; Transport of the SLBP independent Mature mRNA; snRNP Assembly; tRNA processing in the nucleus
Metabolism of proteins: SUMOylation of DNA damage response and repair proteins; SUMOylation of DNA replication proteins; SUMOylation of RNA binding proteins; SUMOylation of SUMOylation proteins; SUMOylation of chromatin organization proteins; SUMOylation of ubiquitinylation proteins
Metabolism: IP3 and IP4 transport between cytosol and nucleus; IP6 and IP7 transport between cytosol and nucleus; IPs transport between nucleus and cytosol; Regulation of Glucokinase by Glucokinase Regulatory Protein
Cell Cycle: Nuclear Pore Complex (NPC) Disassembly
Cellular responses to stimuli: Regulation of HSF1-mediated heat shock response
Immune System: ISG15 antiviral mechanism
Signal Transduction: RHOA GTPase cycle
Gene Ontology:
Molecular function: protein binding
Biological process: microtubule bundle formation; mitotic spindle assembly; nucleocytoplasmic transport; regulation of nucleocytoplasmic transport
Cellular component: membrane; mitotic spindle; nuclear envelope; nuclear membrane; nuclear pore; nucleoplasm; nucleus; spindle pole
Genetic constraint (gnomAD): Loss-of-function variants: 61 observed, 81.95 expected, observed/expected ratio (o/e) 0.74, 90% interval 0.61 to 0.92. The upper end of that interval is the gene's LOEUF score, 0.92, which puts it in group 3 of 6, group 1 being the genes least tolerant of losing a copy. Missense variants: 658 observed, 723.31 expected, observed/expected ratio (o/e) 0.91, 90% interval 0.85 to 0.97. Synonymous variants: 271 observed, 280.37 expected, observed/expected ratio (o/e) 0.97, 90% interval 0.87 to 1.07.
Homologues: Orthologues: chimpanzee AAAS (99% identical), dog AAAS (94% identical), rabbit AAAS (94% identical), mouse Aaas (94% identical), macaque AAAS (93% identical), rat Aaas (92% identical), pig AAAS (90% identical), tropical clawed frog aaas (60% identical), zebrafish aaas (51% identical), Drosophila melanogaster Aladin (27% identical), Drosophila melanogaster CG13137 (19% identical).
Diseases named in the same sentence as AAAS in open-access papers:
AAAS is named in the same sentence as 33 diseases in open-access papers, as found by Europe PMC text mining. Sharing a sentence is not in itself a finding about the gene and the disease. The quoted sentences say what the papers report.
triple-A syndrome (27 papers, 2013 to 2026). Triple A syndrome is a very rare multisystem disease characterized by adrenal insufficiency with isolated glucocorticoid deficiency, achalasia, alacrima, autonomic dysfunction and neurodegeneration. "Allgrove syndrome is inherited in an autosomal recessive pattern and results from mutations in the AAAS gene located on chromosome 12q13, which encodes the ALADIN protein involved in nucleocytoplasmic transport." (PMID 41503296, 2025). "While no human disorder has been associated to one of the three transmembrane nucleoporins, biallelic variants in AAAS, encoding ALADIN, cause triple A syndrome (Allgrove syndrome)." (PMID 39003500, 2024). "Triple A syndrome, caused by autosomal recessively inherited mutations in the AAAS gene is characterized by alacrima, achalasia, adrenal insufficiency, and neurological impairment." (PMID 38544685, 2024). "These include, to name a few, G-protein beta-3 subunit splice variant in hypertension, mutation in AAAS protein causing Triple-A syndrome, and the role of WD11 and STRAP proteins in glioblastoma and carcinogenesis." (PMID 36979349, 2023). "Mutations in the AAAS gene cause triple A syndrome (Allgrove syndrome), which is an autosomal recessive condition characterized by ACTH-resistant adrenal insufficiency and classically associated with reduced or absent tearing (alacrima) and achalasia." (PMID 35495001, 2022). "Dysfunction of many components of the NPC results in human genetic diseases, including triple A syndrome (AAAS) as a result of mutations in ALADIN." (PMID 36351283, 2021). "The so called AAAS gene consists of 16 exons which encode a 546 amino acid protein called ALADIN (Alacrima-Achalasia-adrenal Insufficiency Neurologic disorders)." (PMID 29334914, 2018). "Later, they developed achalasia whereupon Allgrove syndrome was diagnosed clinically and confirmed by DNA sequencing which revealed a c.1331 + 1G > A mutation in the AAAS gene." (PMID 29866068, 2018). "Mutations in the human AAAS gene, coding for the protein ALADIN (alacrima-achalasia-adrenal insufficiency neurologic disorder), lead to the autosomal recessive disorder named triple A syndrome." (PMID 30455725, 2018). "The triple A syndrome gene, designated AAAS, localized on chromosome 12q 13 encodes for a 546 amino acid protein called ALADIN (Alacrimia-Achlasia-Adrenal Insufficiency and Neurologic disorder)." (PMID 29492088, 2017). "The disorder is caused by mutations in AAAS (achalasia-adrenal insufficiency alacrima syndrome) encoding the protein ALADIN (alacrima-achalasia-adrenal insufficiency neurologic disorder)." (PMID 27754849, 2016). "It is caused by mutations in the AAAS gene (achalasia-addisonianism-alacrima syndrome), which disrupts the protein ALADIN (Alacrima-Achalasia-Adrenal insufficiency Neurologic disorder protein), which plays an important role in nucleocytoplasmic transport and cellular stress response." (PMID 40291601, 2025). "Therefore, decreased recruitment of ALADIN to the NE has been advocated as the main mechanism underlying AAAS-related triple A syndrome." (PMID 39003500, 2024). "Protein ALADIN encoded by the AAAS gene is found to be defective in Triple A Syndrome." (PMID 33437289, 2021). "Triple A syndrome is caused by mutations in AAAS encoding the protein ALADIN." (PMID 25867024, 2015). "Triple A syndrome is caused by mutations in the AAAS gene on chromosome 12q13, which consists of 16 exons encoding a 546 amino acid protein termed ALADIN (Alacrima–Achalasia–Adrenal Insufficiency Neurologic disorder)." (PMID 40917361, 2025). "Variants in AAAS, encoding for ALADIN, cause triple A syndrome, also known as Allgrove syndrome (OMIM: 231550)." (PMID 39003500, 2024). "Although a mouse lacking the functional AAAS gene was created, the lack of ALADIN in this mouse did not cause a triple A syndrome-like disease." (PMID 38792545, 2024).
triple-A syndrome (continued). "Triple A syndrome (Allgrove syndrome, OMIM #231550) is caused by autosomal recessively inherited mutations in the AAAS gene on chromosome 12q13 encoding the nuclear pore complex (NPC) protein ALADIN." (PMID 38544685, 2024). "The Allgrove syndrome also known as triple A syndrome (AAAS) is caused by biallelic mutations in the AAAS gene, encoding a 546 amino acid-sized nuclear pore complex protein known as ALADIN (alacrima achalasia adrenal insufficiency neurologic disorder)." (PMID 33563298, 2021). "Triple A syndrome (OMIM #231550), a rare autosomal recessive disorder, is caused by homozygous or compound heterozygous mutations in the AAAS (achalasia-adrenal insufficiency-alacrima syndrome) gene encoding the nucleoporin ALADIN (alacrima-achalasia-adrenal insufficiency neurologic disorder)." (PMID 29362278, 2018). "The variants identified here in the affected individuals all seem to have an effect on the interaction with ALADIN, explaining the high phenotypic overlap with AAAS-related triple A syndrome." (PMID 39003500, 2024). "on an animal model for human triple A syndrome, producing mice lacking a functional AAAS gene." (PMID 38544685, 2024). "Therefore, triple A syndrome should be suspected in HSP patients without a genetic diagnosis, especially if one of the triad symptoms is present, and the AAAS gene should be included in panel screening for HSP." (PMID 30381913, 2018).
Achalasia (19 papers, 2013 to 2025). A disorder of esophageal motility characterized by the inability of the lower esophageal sphincter to relax during swallowing and by inadequate or lacking peristalsis in the lower half of the body of the esophagus. "TAS is caused by genetic alterations in the AAAS gene on chromosome 12q13, which encodes the nuclear pore complex protein termed ALADIN (ALacrima, Achalasia, aDrenal Insufficiency, and Neurologic disorder)." (PMID 39387047, 2024). "Here, we describe an individual with a paternally inherited truncating variant and a maternally inherited, novel missense variant in AAAS presenting with alacrima, achalasia, anejaculation, optic atrophy, muscle weakness, dysarthria, and autonomic dysfunction." (PMID 35570467, 2022). "Recently a similar mechanism was demonstrated to underlie the adrenal dysfunction seen in Triple A, a disorder of adrenal insufficiency, alacrima and achalasia due to mutations in AAAS encoding the protein ALADIN." (PMID 29046340, 2018). "The disease is caused by mutations in the AAAS (achalasia—adrenocortical insufficiency—alacrima syndrome) gene, which encodes the protein ALADIN (alacrima-achalasia-adrenal insufficiency neurologic disorder)." (PMID 25867024, 2015). "Allgrove syndrome (AS) is an autosomal recessive congenital disease, caused by mutations in the AAAS gene, and is characterized by the triad of Addison's disease, achalasia and alacrima." (PMID 26622478, 2015). "The overlap in phenotypes caused by NDC1 and AAAS variants suggests that impaired recruitment of ALADIN to the NPC contributes to the clinical features shared among the two groups of affected individuals, e.g., alacrima, achalasia, and neurological defects." (PMID 39003500, 2024). "This autosomal recessive condition results from biallelic inactivation of the AAAS gene, which encodes a nuclear pore protein called ALADIN (alacrima–achalasia–adrenal insufficiency neurologic disorder)." (PMID 34867779, 2021). "The AAAS gene is located on chromosome 12q13 and encodes the ALADIN protein (alacrima, achalasia, adrenal insufficiency and neurological disorder)." (PMID 29866068, 2018). "The AAAS gene product is the 60 kDa nuclear pore complex (NPC) protein ALADIN (alacrima–achalasia–adrenal insufficiency neurologic disorder)." (PMID 24623797, 2014).
Adrenal insufficiency (12 papers, 2013 to 2024). Insufficient production of steroid hormones (primarily cortisol) by the adrenal glands. "Allgrove syndrome is caused by the mutation of the AAAS gene, causing adrenal insufficiency, achalasia, alacrimia, and neurological impairment." (PMID 37331934, 2023). "Of note, several genes associated with adrenal insufficiency in humans were not differentially expressed during early development; namelyNNT,TXNRD2,AAAS,MCM4 andSGPL1." (PMID 28459107, 2017).
Ataxia (2 papers, 2021 to 2023). Ataxia refers to impaired coordination of voluntary muscle movement. "A subset of FS symptoms, such as dystonia, myoclonus, and ataxia, may be attributed to the downregulation of PLEKHG2, DST, ARX, AAAS, KCTD17, PRDM8, and CRTC1 in FS brains as these genes are downregulated in Q84Pfs-Het brains and play a role in these movement and muscle coordination 43–49." (PMID 37398410, 2023).
familial glucocorticoid deficiency (1 paper, 2022). Familial glucocorticoid deficiency (FGD) is a group of primary adrenal insufficiencies characterized clinically by neonatal hyperpigmentation, hypoglycemia, failure to thrive, and recurrent infections, and biochemically by glucocorticoid deficiency without mineralocorticoid deficiency. "Based on the presence of a micropenis and the later onset of hyperpigmentation, along with failed ACTH stimulation test and XY karyotype, we suspected the diagnosis of mutations of NR0B1, CYP11A1, and STAR genes or familial glucocorticoid deficiency (FGD) (MC2R, MRAP, NNT, and AAAS)." (PMID 36407315, 2022).
Fanconi anemia (1 paper, 2025). Fanconi anemia (FA) is a hereditary DNA repair disorder characterized by progressive pancytopenia with bone marrow failure, variable congenital malformations and predisposition to develop hematological or solid tumors. "Our finding of the deletion occurring between AluY pairs is consistent with this observation, and similar mechanisms have been observed in several diseases, including Fanconi anemia, SPAST, and AAAS genes." (PMID 40033291, 2025).
Intellectual disability (1 paper, 2020). "Additional proteins included AAAS, ACSF3, and ADSSL1, which are known to be associated with neurodevelopmental abnormalities that present with intellectual disability and impaired learning and memory." (PMID 32850779, 2020).
mesothelioma (1 paper, 2023). A usually malignant and aggressive neoplasm of the mesothelium which is often associated with exposure to asbestos. "With this system, we confirmed that knockdown at the TSS of NDC1 and AAAS, two components of the nuclear pore complex, or silencing a putative enhancer of the nuclear receptor NR2F2, decreased the proliferation of mesothelioma cell lines but not of uveal melanoma." (PMID 37400441, 2023).
Myalgia (1 paper, 2025). "However, central in this core net one can find the genes NF2 and BRAF (associated to HPO-class BN and ACTH), EP300 (associated to HPO-class BN), AAAS (associated to HPO-class ACTH) and PTPN2 (associated to Myalgia)." (PMID 40831500, 2025).
cancer (2 papers, 2023 to 2025). A tumor composed of atypical neoplastic, often pleomorphic cells that invade other tissues. "Among them AAAS, HK3, and ADPGK the expression of three genes was obviously raised in cancer samples and was significantly correlated with prognosis." (PMID 41035662, 2025).
genetic disease (2 papers, 2019 to 2021). "Further variable members of the NPC were found to be ALADIN (AAAS) (p = 0.12, one-sided t test), which potentially binds to transmembrane nucleoporins and has been linked to genetic disease, as well as NUP50 (FDR-corrected p = 0.022, one-sided t test), a subunit involved in active nuclear import." (PMID 31031010, 2019).
AAAS also shares sentences with these, for which no sentence is quoted: Neurologic disorder (5 papers); Addison disease (2); adrenocortical carcinoma (2); infertile (2); adrenal hypoplasia (1); adrenal hypoplasia congenita (1); adrenocortical insufficiency (1); adrenocortical tumour (1); autonomic dysfunction (1); cerebellar ataxia (1); Congenital adrenal hypoplasia (1); Dystonia (1); glioblastoma (1); Hypertension (1); liver disease (1); Micropenis (1); motor neuron disease (1); neurodegenerative disease (1); optic atrophy (1); polyneuropathy (1); uveal melanoma (1); X-linked adrenoleukodystrophy (1).